LRRK1 (leucine rich repeat kinase 1)
Description:
Serine/threonine-protein kinase which phosphorylates RAB proteins involved in intracellular trafficking. Phosphorylates RAB7A; this activity is dependent on protein kinase C (PKC) activation. Plays a role in the negative regulation of bone mass, acting through the maturation of osteoclasts (By similarity).
Synonyms: KIAA1790; FLJ23119; ROCO1; RIPK6; OSMD
Tractability: Small molecule: a structure with a bound ligand is known; it belongs to a druggable protein family. Antibody: UniProt places it where antibodies can reach, with high confidence; its Gene Ontology location is reachable by antibodies, with medium confidence. PROTAC: ubiquitination databases record sites on it.
Gene: Protein-coding gene on chromosome 15 (100,919,327 to 101,078,257, forward strand). Ensembl gene ENSG00000154237.
Subcellular location: Cytoplasm; Cell membrane
Subcellular location (Human Protein Atlas): Cytosol; Mitochondria
Gene Ontology:
Molecular function: identical protein binding; protein binding; ATP binding; protein kinase activity; protein serine kinase activity; protein serine/threonine kinase activity
Biological process: positive regulation of canonical Wnt signaling pathway; positive regulation of signal transduction
Cellular component: cytosol; cytoplasm; plasma membrane
Genetic constraint (gnomAD): Loss-of-function variants: 106 observed, 197.44 expected, observed/expected ratio (o/e) 0.54, 90% interval 0.46 to 0.63. The upper end of that interval is the gene's LOEUF score, 0.63, which puts it in group 2 of 6, group 1 being the genes least tolerant of losing a copy. Missense variants: 2,252 observed, 2,655.6 expected, observed/expected ratio (o/e) 0.85, 90% interval 0.82 to 0.88. Synonymous variants: 1,137 observed, 1,118.9 expected, observed/expected ratio (o/e) 1.02, 90% interval 0.97 to 1.07.
Homologues: Orthologues: chimpanzee LRRK1 (99% identical), macaque LRRK1 (98% identical), guinea pig LRRK1 (92% identical), dog LRRK1 (91% identical), pig LRRK1 (91% identical), rabbit LRRK1 (90% identical), mouse Lrrk1 (89% identical), rat Lrrk1 (88% identical), tropical clawed frog lrrk1 (67% identical), zebrafish lrrk1 (42% identical). Paralogues in human: LRCH3 (10% identical), LRCH1 (9% identical), LRCH2 (9% identical), LRCH4 (9% identical), SCRIB (9% identical), LRRC7 (8% identical), ERBIN (8% identical), PHLPP1 (7% identical), PHLPP2 (7% identical), MFHAS1 (7% identical), PIDD1 (6% identical), LRRD1 (5% identical), and 19 more.
Diseases named in the same sentence as LRRK1 in open-access papers:
LRRK1 is named in the same sentence as 33 diseases in open-access papers, as found by Europe PMC text mining. Sharing a sentence is not in itself a finding about the gene and the disease. The quoted sentences say what the papers report.
osteopetrosis (16 papers, 2016 to 2025). Osteopetrosis, also known as marble bone disease, is a descriptive term that refers to a group of rare, heritable disorders of the skeleton characterized by increased bone density on radiographs. "Global knockout (KO) of the Lrrk1 gene in mice causes severe osteopetrosis because of the failure of osteoclasts to resorb bone." (PMID 40282191, 2025). "Mutations in LRRK1 are linked to the rare bone diseases osteopetrosis and osteosclerotic metaphyseal dysplasia." (PMID 40465731, 2025). "The patient with a loss of LRRK1 function suffered from severe osteopetrosis at the metaphysis of the long and short tubular bones, as observed in the Lrrk1 KO mice." (PMID 37106712, 2023). "It would also be vital to study LRRK1 activity in osteoclasts given loss of LRRK1 activity in both humans and mice results in severe osteopetrosis." (PMID 33459343, 2021). "Deficiency of Lrrk1 in mice causes a severe osteopetrosis in the metaphysis of the long bones and vertebrae bones, which makes LRRK1 an attractive alternative drug target for the treatment of osteoporosis and other high-turnover bone diseases." (PMID 28326224, 2017). "Previous studies have revealed that knockout (KO) of Lrrk1 in mice causes severe osteopetrosis, and a human mutation of Lrrk1 leads to osteosclerotic metaphysial dysplasia." (PMID 27600824, 2016). "Increasing reports of LRRK1 variants in this phenotype raise the question of whether LRRK1 should be included in targeted osteopetrosis panels." (PMID 37920250, 2023). "We found that genes associated with osteopetrosis have undergone positive selection (CSF1R and LRRK1) or pseudogenized (FAM111A and IGSF23) in the African manatee, potentially contributing to the dense bone formation." (PMID 39092175, 2024). "LRRK1-KO mice exhibited severe osteopetrosis, reduced bone resorption, and increased bone mineralization." (PMID 39092175, 2024). "Mice with disruption of Lrrk1 exhibited severe osteopetrosis phenotypes in the femurs, tibias, and vertebrae due to dysfunction of mature osteoclasts." (PMID 27600824, 2016). "Unlike LRRK2, LRRK1 is not linked to PD; loss of function of LRRK1 is linked to the rare bone diseases osteopetrosis and osteosclerotic metaphyseal dysplasia." (PMID 40523620, 2025). "Mice without the Lrrk1 gene present with severe osteopetrosis, a disease that causes bones to become overly dense and is the opposite of osteoporosis in vertebral and tubular bones because of the functional failure of osteoclasts to resorb bone." (PMID 40282191, 2025). "Mice with deletion of Lrrk1 manifested an osteopetrosis phenotype." (PMID 37106712, 2023). "LRRK1 knock-out mice also display severe osteopetrosis that is not observed in LRRK2 deficient animals." (PMID 33459343, 2021). "Given the links of LRRK1 to osteopetrosis, inhibiting this enzyme would be undesirable." (PMID 33459343, 2021). "Finally, recent research in LRRK1 knockout mice revealed a negative regulatory role of LRRK1 for bone mass, thus, providing a link between LRRK1 and osteopetrosis." (PMID 30609797, 2019). "The authors, however, reported that targeted disruption of Lrrk1 leads to severe osteopetrosis." (PMID 28103901, 2017). "Though CLIP-170 is involved in cytoskeleton arrangement, male mice with disruption of CLIP-170 exhibited abnormal sperm and reduced fertility without skeletal phenotypes, whereas Lrrk1-deficient males showed normal fertility but severe osteopetrosis." (PMID 27600824, 2016). "Consistent with our observations in the Lrrk1 KO mouse model, our recent human genetic studies have identified a severe osteopetrosis phenotype at the vertebra and the metaphysis of long and short tubular bones in a patient with Lrrk1 deletion and frame-shifted mutation." (PMID 27600824, 2016).
osteopetrosis (continued). "In support of the key involvement of OSTM1 in LRRK1 signal pathways are the findings that both OSTM1 and CLC7 play a critical role in regulating osteoclast function by providing extracellular acidification and ablation of either Ostm1 or Clc7 in mice, causing severe osteopetrosis." (PMID 37106712, 2023). "Extremely rare forms of osteoclast-rich osteopetrosis are caused by defects in the carbonic anhydrase 2 (CA2), pleckstrin homology and RUN domain-containing M1 (PLEKHM1), leucine-rich repeat kinase 1 (LRRK1) and melanocyte-inducing transcription factor (MITF) genes." (PMID 33970241, 2021).
Parkinson disease (14 papers, 2012 to 2025). A progressive degenerative disorder of the central nervous system characterized by loss of dopamine producing neurons in the substantia nigra and the presence of Lewy bodies in the substantia nigra and locus coeruleus. "We identify two LRRK1 mutations (K746G and I1412T), equivalent to the LRRK2 R1441G and I2020T Parkinson's mutations, that enhance LRRK1 mediated phosphorylation of Rab7A." (PMID 33459343, 2021). "Furthermore, Parkinson’s disease-linked mutations in LRRK2 are typically autosomal dominant gain-of-function while those in LRRK1 are autosomal recessive loss-of-function." (PMID 37857821, 2023). "In addition, one report using whole exome sequencing in two Parkinson’s disease (PD) patients identified variants in LRRK1 (among other genes)." (PMID 35996156, 2022). "We next studied whether mutations equivalent to the common Parkinson's causing LRRK2 mutations would affect LRRK1's ability to phosphorylate Rab7A in cells." (PMID 33459343, 2021). "LRRK1 is related to the familial Parkinsonism gene product Park8 (also known as LRRK2) and belongs to the ROCO family of proteins, which contain a Ras of complex proteins (ROC) GTPase domain and a MAPKKK-like kinase domain." (PMID 36254578, 2022). "LRRK1 loss of function mutations cause the bone disorder osteosclerotic metaphyseal dysplasia, whereas LRRK2 missense mutations that enhance kinase activity cause Parkinson's disease." (PMID 36040231, 2022). "LRRK1 is related to the familial Parkinsonism gene product Park8 (LRRK2)." (PMID 36254578, 2022). "Interestingly, the striking similarity on the overall structures of LRRK2 and LRRK1 suggests that the specificity of LRRK2 versus LRRK1 in its role in Parkinson’s disease must be sought at another level." (PMID 28819229, 2017). "Previous studies have linked mutations in the Lrrk2 but not Lrrk1 gene in humans to Parkinson disease, although both Lrrk1 and Lrrk2 are expressed in multiple tissues including macrophage precursors." (PMID 27600824, 2016). "Furthermore, a Parkinson's causing mutation in VPS35[D620N] stimulates LRRK2 activity without impacting LRRK1." (PMID 36040231, 2022). "However, only mutations in LRRK2, but not in LRRK1, have been identified as a cause of familial Parkinson's disease (PD)." (PMID 22952686, 2012). "Genetic evidence in humans, points towards LRRK1 regulating bone biology and LRRK2 contributing to Parkinson's disease." (PMID 33459343, 2021). "Also, given that LRRK2 is a key player in the pathogenesis of Parkinson’s disease while LRRK1 is not, the comparison of structures of both LRRK proteins may yield clues to LRRK2’s pathological functions and aid in designing novel LRRK2 targeting therapeutics." (PMID 28819229, 2017).
Metaphyseal dysplasia (10 papers, 2019 to 2025). The presence of dysplastic regions in metaphyseal regions. "Mutations in LRRK1 have been shown to cause osteosclerotic metaphyseal dysplasia [MIM: 615198], a rare skeletal dysplasia characterized by osteosclerosis of the long bones." (PMID 35996156, 2022). "LRRK1 (leucine-rich repeat kinase 1) gene mutation was found in a single patient affected by osteosclerotic metaphyseal dysplasia, that specifically compromises the methaphyses of long bones, vertebral endplates, costal ends and margin of flat bones." (PMID 30837952, 2019). "In conclusion, we described a 40-year-old patient with osteosclerotic metaphyseal dysplasia caused by a homozygous variant in the LRRK1 gene, resulting in multiple fractures of the long bones without other features of the disease, adding to the phenotypic variation of OSMD." (PMID 37614307, 2023). "Thus far, osteosclerotic metaphyseal dysplasia, which is a rare form of skeletal dysplasia, is the only human condition thought to be caused by variants in LRRK1." (PMID 32238911, 2020). "Autosomal recessive variants in the LRRK1 gene that cause frameshift or truncating mutations in the C-terminal domain of the LRRK1 protein, likely lead to loss of function and are associated with osteosclerotic metaphyseal dysplasia, a severe metabolic bone disorder." (PMID 40371391, 2025). "Mutations in the LRRK1 (leucine-rich repeat kinase 1)gene are responsible for osteosclerotic metaphyseal dysplasia.The LRRK1 gene consists of 34 exons spanningabout 150 bp on chromosome 15q26.3." (PMID 37465191, 2023). "LRRK1 and LRRK2 phosphorylate distinct subsets of RAB proteins, downstream effectors of LRRK activity, and mutations of LRRK1 lead to a rare bone condition, osteosclerotic metaphyseal dysplasia, also indicative of divergent functionality." (PMID 34397087, 2021).
osteosclerotic metaphyseal dysplasia (6 papers, 2018 to 2025). "Osteosclerotic metaphyseal dysplasia (OSMD) is a very rare autosomal-recessive disease caused by mutations in the leucine-rich repeat kinase 1 (LRRK1) gene." (PMID 37614307, 2023). "Autosomal recessive variants that induce frameshift or truncating mutations within the C-terminal domain of LRRK1, that are likely loss of function, cause a severe metabolic bone disorder termed osteosclerotic metaphyseal dysplasia (OSMD)." (PMID 33459343, 2021). "A genetic disease, osteosclerotic metaphyseal dysplasia (OSMD), which is characterized by severe bone abnormalities and osteoporosis, is caused by mutations in LRRK1 which eliminate LRRK1 kinase activity." (PMID 37558661, 2023). "However, LRRK1 has rarely been reported to be associated with a human disease except that one family was found to carry LRRK1 mutations linked to the osteosclerotic metaphyseal dysplasia (OSMD), while LRRK2 has been strongly associated with PD, Alzheimer’s disease (AD), and immune disorders." (PMID 30562929, 2018).
osteoporosis (4 papers, 2017 to 2025). A condition of reduced bone mass, with decreased cortical thickness and a decrease in the number and size of the trabeculae of cancellous bone (but normal chemical composition), resulting in increased fracture incidence. "We are particularly interested in LRRK1 because LRRK1 is an ideal drug target, and partial inhibition of the LRRK1 function with small molecular inhibitors is assumed to enhance bone density and strength for the treatment of osteoporosis." (PMID 40282191, 2025). "Therefore, we can hypothesize that the severe osteoporosis and osteolysis observed in NGPS cells might be associated with an increased level or activity of LRRK1 and/or PAFAH1B1." (PMID 39956852, 2025).
osteosclerosis (3 papers, 2017 to 2022). Abnormally high bone density. "He had unique metadiaphyseal splaying and osteosclerosis, vertebral end‐plate osteosclerosis, and cortical thinning of long bones but no mutation was detected of SLC29A3, TNFRSF11A, TCIRG1, LRRK1, or CSF1R associated with DSS." (PMID 35991533, 2022).
T-cell acute lymphoblastic leukemia (2 papers, 2020 to 2022). Acute lymphoblastic leukemia of T-cell origin. "Furthermore, LINC00511 enhanced T-cell acute lymphoblastic leukemia (T-ALL) progression by inducing miR-195-5p/LRRK1 axis." (PMID 35893227, 2022).
bone osteosarcoma (1 paper, 2023). A usually aggressive malignant bone-forming mesenchymal neoplasm arising from the bone. "To complement our in vitro studies, we transfected the U2OS human bone osteosarcoma epithelial cell line with plasmids expressing WT LRRK1 and the R1290A/R1293A, K1270M, Y971F, and K746G mutants." (PMID 37558661, 2023).
colon cancer (1 paper, 2020). "Among the predictions for colon cancer targets, the top gene, LRRK1, was not supported by text mining data from Open Targets." (PMID 32612205, 2020).
colorectal cancer (1 paper, 2020). A primary or metastatic malignant neoplasm that affects the colon or rectum. "However, the mouse ortholog of this gene has been identified as a potential colorectal cancer (CRC) driver in a mutagenesis screen, and LRRK1 is frequently deleted in human CRC28." (PMID 32612205, 2020).
neuroblastoma (1 paper, 2022). Neuroblastoma (NB) is the most common solid, extracranial childhood tumor. "Previous work by the Taymans and Greggio laboratories had previously reported the Ser1075 and Thr1075 sites as well as three other sites we did not detect in our analysis (Ser249, Ser1241 and Thr1287) from SH-SY5Y neuroblastoma cell lines stably expressing 3xFlag-LRRK1." (PMID 36040231, 2022).
skeletal dysplasia (3 papers, 2019 to 2022). Any Mendelian diseases that affects growth and development of the skeleton. "Importantly, skeletal phenotypes were described for Fam20c (non-lethal Raine syndrome), Lrrk1 (osteosclerotic metaphyseal dysplasia), Pappa2 (short stature), Sfrp4 (Pyle's disease), and Slc10a7 (skeletal dysplasia) prior to knowledge of the human skeletal dysplasias when mutated in humans." (PMID 32117046, 2019).
cancer (2 papers, 2020 to 2022). A tumor composed of atypical neoplastic, often pleomorphic cells that invade other tissues. "Incubation of cells with increasing doses of the LXS-196 (Darovasertib), a PKC inhibitor, that is currently in human clinical cancer trials, and highly specific, resulted in a concentration dependent inhibition of immunoprecipitated LRRK1 kinase activity, with an IC50 of ∼40 nM." (PMID 36040231, 2022). "In the COSMIC database, 78, 114, 113, and 83 studies confirmed the correlation between HNRNPA2B1, BPTF, LRRK1, and PUM1 with cancer, respectively." (PMID 32300588, 2020). "Furthermore, after network analysis, EPRS, HNRNPA2B1, BPTF, LRRK1, and PUM1 were demonstrated to have a broad correlation with cancers." (PMID 32300588, 2020).
bone disorder (1 paper, 2022). "Rare recessive loss of function mutations in LRRK1 lead to a serious bone disorder termed osteosclerotic metaphyseal dysplasia." (PMID 36040231, 2022).
tumor (1 paper, 2016). "LRRK1 might also regulate survival and proliferation of tumor cells, based on the observation that overexpression of LRRK1 allows cells to proliferate under serum-deprived conditions." (PMID 27166870, 2016).
LRRK1 also shares sentences with these, for which no sentence is quoted: Parkinson's (3 papers); genetic disease (2); acute lymphoblastic leukemia (1); Alzheimer disease (1); attention deficit-hyperactivity disorder (1); autism (1); bipolar disorder (1); diffuse sclerosis (1); dysplasia (1); Huntington disease (1); immune disorders (1); lower respiratory tract infection (1); lymphoma (1); major depressive disorder (1); metabolic bone disorder (1); neurodegenerative disease (1); osteonecrosis of the (1); schizophrenia (1).